SNORD114-21 (small nucleolar RNA, C/D box 114-21)
Synonyms: 14q(II-21)
Gene: Small nucleolar RNA gene on chromosome 14 (100,981,975 to 100,982,046, forward strand). Ensembl gene ENSG00000272344.
Gene Ontology:
Biological process: RNA processing
Cellular component: nucleolus
Homologues: Orthologues: chimpanzee SNORD114-21 (97% identical), macaque SNORD114-21 (97% identical), mouse Gm25854 (72% identical), mouse Gm23347 (69% identical), rat LOC120093407 (58% identical). Paralogues in human: SNORD114-22 (93% identical), SNORD114-15 (92% identical), SNORD114-28 (92% identical), SNORD114-23 (90% identical), SNORD114-26 (90% identical), SNORD114-9 (90% identical), SNORD114-25 (89% identical), SNORD114-3 (89% identical), SNORD114-6 (89% identical), SNORD114-5 (86% identical), SNORD114-13 (85% identical), SNORD114-14 (85% identical), and 26 more.